FBL (fibrillarin rRNA 2'-O-methyltransferase)
Diseases named in the same sentence as FBL in open-access papers (continued):
Sharing a sentence is not in itself a finding about the gene and the disease.
viral infection (6 papers, 2016 to 2026). "This review aims to examine the fundamental structure and functionality of FBL proteins and discuss recent developments in research in various contexts, such as viral infections, autoimmune diseases, reproductive development, cellular stress, and cancer." (PMID 39605984, 2024). "The role of FBL in viral infection extends beyond binding viral proteins, as demonstrated by functional screening, which identified RNA 2′-O-Me FBL as a facilitator of viral infection." (PMID 39605984, 2024). "FBL and its mediated RNA 2′-O-methylation (Nm) modification can inhibit innate immunity and promote viral infection." (PMID 37889708, 2023). "Here we found that Nm RNA modification and RNA 2’-O-methyltransferase FBL also regulate viral infection." (PMID 35464456, 2022). "FBL, as a nucleolar protein, is also a potential target for viral infection." (PMID 39605984, 2024). "Also, FBL and its mediated RNA Nm modifications inhibit innate immune response, which can promote virus entry into macrophages to facilitate viral infection." (PMID 38934770, 2024). "Down-regulation of FBL can block viral infection of macrophages and inhibit viral infection." (PMID 37889708, 2023). "Down-regulation of FBL inhibited viral infection through blocking virus entry into macrophages." (PMID 35464456, 2022). "Therefore, our finding reveals a new role of FBL and its mediated RNA Nm modifications in facilitating viral infection and inhibiting innate immune response, adding mechanistic insight to the RNA modifications in infection and immunity." (PMID 35464456, 2022). "We investigated whether FBL and HeV-M colocalize in the nucleolus during live virus infection." (PMID 27010548, 2016). "Our results reveal that FBL inhibits the expression of IFN-I and ISGs by suppressing the innate immune activation, which promotes virus entry and further viral infection in macrophages." (PMID 35464456, 2022). "Paramyxovirinae M main role in viral infection is viral budding and we have shown that viral budding still occurs even in the absence of FBL even though its efficiency was decreased, which suggests that at later times in HeV infection FBL could play a role in M trafficking and viral budding." (PMID 27010548, 2016). "In order to investigate the underlying mechanism of FBL in facilitating VSV entry into macrophages, we performed RNA-seq and found that mRNA expressions of many ISGs were up-regulated in Fbl+/- RAW264.7 cells at the steady state without viral infection." (PMID 35464456, 2022). "By functional screening of eight RNA 2’-O-methyltransferases, in this study we found that FBL inhibits innate immune response by suppressing the expression of IFN-I and ISGs in macrophages, which can promote virus entry into macrophages to facilitate viral infection." (PMID 35464456, 2022).
prostate carcinoma (4 papers, 2021 to 2025). A carcinoma that arises from epithelial cells of the prostate gland. "In this study, we investigated the association of two nucleolar proteins, nucleophosmin (NPM1), and fibrillarin (FBL), with prostate cancer (PCa) aggressiveness and progression." (PMID 40705480, 2025). "Overexpression of FBL was found in breast, prostate cancers and squamous cell cervical carcinoma." (PMID 35991567, 2022). "In prostate cancer, however, the expression of FBL can be upregulated by MYC." (PMID 36004921, 2022). "Importantly, FBL is highly expressed in human breast and prostate cancer and its expression positively correlates with poor prognosis." (PMID 33564819, 2021).
liver cancer (3 papers, 2022 to 2025). An epithelial or non-epithelial malignant neoplasm that arises from the liver. "In this study, we found that fludarabine phosphate is a new inhibitor of FBL and that its combination with lenvatinib could improve the treatment of liver cancer." (PMID 40289107, 2025).
acute myeloid leukaemia (2 papers, 2017 to 2025). "FBL is frequently overexpressed in cancers, including breast, pancreas, lung, colon, prostate, liver, and acute myeloid leukaemia (AML)." (PMID 41463151, 2025).
diabetes (2 papers, 2023 to 2024). "Novel targets include MYO18A, SEC16A, CCNB1, MAD2L1, hsa-mir-4315, hsa-mir-6134, hsa-mir-9500, KIFC3, FBL (fibrillarin), TUBA1A and GFI1B might have crucial biologic functions in the pathogenesis of patients with diabetes mellitus and obesity." (PMID 36837510, 2023).
glioblastoma (2 papers, 2023 to 2024). The most malignant astrocytic tumor (WHO grade IV). "Glioblastoma frequently expressed higher levels of FBL, NOP56, and NOP58 compared to non-tumor specimens in The Cancer Genome Atlas (TCGA) RNA-seq data." (PMID 37980347, 2023).
neuroblastoma (2 papers, 2020 to 2026). Neuroblastoma (NB) is the most common solid, extracranial childhood tumor. "The positive correlation between C-MYC and FBL expression in neuroblastoma further supports the established role of C-MYC in enhancing ribosome biogenesis through upregulation of ribosomal RNA modification enzymes and assembly factors." (PMID 41614906, 2026). "Interestingly, six genes ARMC6, DCTPP1, EIF4G1, ELOVL6, FBL and PRMT1 were associated with the clinical overall survival of neuroblastoma in both TARGET and GSE85047 datasets." (PMID 32593299, 2020). "Therefore, functions and prognosis of ARMC6, DCTPP1, EIF4G1, ELOVL6 and FBL in neuroblastoma should be further studied." (PMID 32593299, 2020). "In the neuroblastoma group, a statistically significant positive correlation was identified between C-MYC and FBL expression." (PMID 41614906, 2026). "The present study suggested new prognostic markers of ARMC6, DCTPP1, EIF4G1, ELOVL6 and FBL in neuroblastoma and highlighted the combinational prognostic significance of MYCN amplification and EIF4G1 expression in patients with neuroblastoma." (PMID 32593299, 2020). "However, the functions and prognosis of ARMC6, DCTPP1, EIF4G1, ELOVL6 and FBL in neuroblastoma were not reported." (PMID 32593299, 2020). "In the neuroblastoma group, a statistically significant positive correlation was identified between C-MYC and FBL expression (p = 0.004), while no other correlations were found to be significant." (PMID 41614906, 2026).
prostate adenocarcinoma (2 papers, 2024 to 2025). "The mRNA expression of NPM1 and FBL was increased in PCa specimens compared to normal prostatic tissues in the prostate adenocarcinoma [The Cancer Genome Atlas (TCGA)] dataset accessed through UALCAN (The University of ALabama at Birmingham CANcer data analysis Portal)." (PMID 40705480, 2025).
autoimmune disease (1 paper, 2019). A disorder resulting from loss of function or tissue destruction of an organ or multiple organs, arising from humoral or cellular immune responses of the individual to their own tissue constituents. "Of course, in the case of autoimmune diseases, the development of autoantibodies against FBL is rather a consequence and not a cause of the pathology." (PMID 30764532, 2019).
B cell lymphoma (1 paper, 2017). "As a feasibility test, we first queried predicted DH for three genes FBL, LIN28A and BLMH in P493-6 B cell lymphoma (for which no public DNase-seq data are available) and H9 human embryonic stem cells." (PMID 29051481, 2017).
breast tumors (1 paper, 2022). "So far, all studies, including ours, demonstrated that FBL is overexpressed in breast tumors and is associated with poor patient outcome." (PMID 35545761, 2022). "At the genomic level, we first observed that breast tumors expressing low FBL mRNA levels had significantly lower number of copy alterations or mutation counts than breast tumors exhibiting high FBL mRNA levels, supporting that the two FBL-related tumor groups are different." (PMID 35545761, 2022). "In a second independent series of 661 breast samples, breast tumors expressing low FBL mRNA levels also displayed poor survivals (TCGA series, OS P = 0.0057, DFS P = 0.0037)." (PMID 35545761, 2022). "Overall, it appears that breast tumors overexpressing and underexpressing FBL exhibit different clinical characteristics and gene expression profiles, in particular regarding ribosome production and mRNA translation." (PMID 35545761, 2022). "Based on this FBL-related stratification, Kaplan–Meier curves revealed that patients harboring breast tumors expressing different FBL mRNA levels displayed distinct OS and DFS (P = 0.0128 and 0.0053, respectively)." (PMID 35545761, 2022). "Using 3,275 non-metastatic primary breast tumors, we analysed FBL mRNA expression levels and protein nucleolar organisation." (PMID 35545761, 2022).
COVID-19 (1 paper, 2022). A disease caused by infection with severe acute respiratory syndrome coronavirus 2. "The down-regulation of FBL in severe patients of COVID-19 with 50% lethality frequency was shown to play pivotal roles in impairing ribosome function and in cell cycle arrest, maximizing the transcription and translation of the SARS-CoV-2 genes while decreasing the production of host genes." (PMID 36362378, 2022).
endometrial cancer (1 paper, 2025). Primary or metastatic malignant neoplasm involving the endometrium (mucous membrane that lines the endometrial cavity). "In endometrial cancer, the SNORD104/FBL complex enhances PARP1 mRNA translation to drive tumor progression, while FBL silencing disrupts this process, leading to tumor growth inhibition." (PMID 41463151, 2025).
esophageal squamous cell carcinoma (1 paper, 2025). Esophageal squamous cell carcinoma (ESCC) is a type of esophageal carcinoma (EC) that can affect any part of the esophagus, but is usually located in the upper or middle third. "An omics study identified enhanced FBL expression in esophageal squamous cell carcinoma and is associated with poor survival of patients." (PMID 40705480, 2025).
gastric cancer (1 paper, 2024). A primary or metastatic malignant neoplasm involving the stomach. "The interaction between RPs and FBL suggested by RibosomeR may imply altered ribosome biogenesis in gastric cancer." (PMID 39086661, 2024).
glioma (1 paper, 2023). A benign or malignant brain and spinal cord tumor that arises from glial cells (astrocytes, oligodendrocytes, ependymal cells). "FBL, NOP56, and NOP58 expression increased with tumor grade in the Chinese Glioma Genome Atlas (CGGA), and FBL/NOP58 were associated with poor patient survival." (PMID 37980347, 2023).
melanoma (1 paper, 2022). A malignant, usually aggressive tumor composed of atypical, neoplastic melanocytes. "Thus, FBL could have a role in tumor progression and could affect the clinical outcome of patients through alteration of translational regulation in melanoma." (PMID 35991567, 2022).
metastatic disease (1 paper, 2025). "These insights open new avenues for targeting nucleolar activity in advanced CRC and highlight FBL as a potential biomarker and therapeutic target in metastatic disease." (PMID 41463151, 2025).
nevus (1 paper, 2022). Nevus (or naevus, plural nevi or naevi, from nævus, Latin for "birthmark") is the medical term for sharply circumscribed[1] and chronic lesions of the skin or mucosa. "In our study, we found that the low expression of FBL in SKCM tissues compared to nevus tissues was observed in multiple datasets, and survival analysis showed that the high expression of FBL was related to a worse prognosis in SKCM." (PMID 35991567, 2022).
prostate tumors (1 paper, 2015). "Our results showed that JARID1B and FBL proteins are co-localized in a majority of epithelial cells in prostate tumors of Ptenpc−/−; Trp53pc−/−; Skp2−/− mice, but not in that of Ptenpc−/−; Trp53pc−/− mice." (PMID 25596733, 2015).
scleroderma (1 paper, 2025). Scleroderma is a rare autoimmune connective tissue disorder characterized by abnormal hardening of the skin and, sometimes, other organs. "FBL was first detected in fibrillar and granular regions of the nucleolus in autoimmune serum of patients with scleroderma, as well as in Cajal bodies (CBs)." (PMID 41373481, 2025).
Sepsis (1 paper, 2023). Sepsis is defined as life-threatening organ dysfunction caused by a dysregulated host response to infection. "Microarray analysis has indicated abnormalities in the expression of immune-related genes in children with sepsis, including FYN, FBL, ATM, WDR75, FOXO1, and ITK." (PMID 36855207, 2023).
systemic lupus erythematosus (1 paper, 2022). An autoimmune multi-organ disease typically associated with vasculopathy and autoantibody production. "We retrieved gene expression omnibus (GEO) dataset GDS4185 which contains FBL mRNA expression data of isolated CD4+ T cells and CD19+ B cells from the blood of Systemic Lupus Erythematosus (SLE) patients and healthy controls." (PMID 35464456, 2022).
thyroid cancer (1 paper, 2025). "We found that a fraction of pY397 FAK co-localizes with the nucleolar marker, FBL, in the panel of BRAF- and RAS-mutant thyroid cancer cell lines derived from PTC or ATC tumors." (PMID 40458728, 2025).
cancer (31 papers, 2018 to 2026). A tumor composed of atypical neoplastic, often pleomorphic cells that invade other tissues. "Previous studies have linked the expression of FBL to cancer." (PMID 40705480, 2025). "On the other hand, FBL, a well-established nucleolar methyltransferase that catalyzes the methylation of rRNA and RPs, has been linked to the enhanced resistance of cancer cells to DNA damage caused by DNA crosslinkers, i.e., cisplatin, camptothecin, and etoposide." (PMID 39410048, 2024). "In addition, similarly to FBL, the overexpression of dyskerin has also been associated with cancer, likely contributing via the dysregulated rRNA pseudouridylation, but precise mechanism is not known." (PMID 31026227, 2019). "Collectively, these results demonstrate that FBL contributes to the growth of HCC cancer cells both in vitro and in vivo." (PMID 40289107, 2025). "To investigate the role of FBL, we used SW-480 and SW-620 cells as an isogenic model for cancer progression and metastasis." (PMID 41463151, 2025). "FBL is critical for maintaining nucleolar integrity and plays a pivotal role in cancer biology through its interactions with snoRNAs." (PMID 41463151, 2025). "While the role of FBL in cancer is well documented, its involvement in metastasis is less understood." (PMID 41463151, 2025). "The observed suppression of key oncogenic pathways and CREB phosphorylation upon FBL inhibition suggests that FBL integrates ribosomal regulation with cancer cell signaling." (PMID 41463151, 2025). "Elevated FBL expression has been reported in multiple cancers, where it promotes ribosome biogenesis, enhances proliferation, and supports oncogenic translational programs." (PMID 41568368, 2025). "In cancer cells, elevated FBL correlates with increased 2′-O-methylated mRNAs in key cancer pathways, highlighting its involvement in translation control and post-transcriptional regulation." (PMID 41463151, 2025). "FBL inhibition reduces tumor progression and enhances sensitivity to 5-FU, highlighting its dual role in ribosome biogenesis and cancer aggressiveness." (PMID 41463151, 2025). "Here, we characterized FBL as a cancer-promoting gene that is profoundly upregulated and essential for cell proliferation." (PMID 40289107, 2025). "This translocation of NCL and FBL by honey markedly affected the proliferation and survival of cancer cells in our study." (PMID 39410048, 2024). "Hassouni emphasized the correlation between FBL and cancer ribosomal biogenesis, and proposed that targeting FBL can reduce the toxic effects of anticancer therapy, making it a promising cancer treatment strategy." (PMID 39605984, 2024). "Gene set enrichment analysis (GSEA) of differentially expressed genes demonstrated that genes regulated by FBL are related to cancer proliferation, poor survival, neural stem cells, and rRNA expression." (PMID 37980347, 2023). "Our data demonstrating that FBL, but not the other components of the rRNA 2’O-Me maturation complex, is an independent marker of poor prognosis, support the important role of FBL in cancer." (PMID 35545761, 2022). "FBL has also been assigned as a promising target in cancers, suggesting the power of functional genomics in identifying oncogene-specific vulnerabilities and the accountability of our analyses." (PMID 35039048, 2022). "FBL is involved in rDNA synthesis during the interphase of the cell cycle, and is required for normal nuclear morphology and cancer cell growth." (PMID 34586744, 2021).